KRAS (KRas proto-oncogene, GTPase)
Diseases named in the same sentence as KRAS in open-access papers (continued):
Sharing a sentence is not in itself a finding about the gene and the disease.
tumor (continued). "In gastric and colorectal cancer (CRC) cell lines, abnormal activation of KRAS upregulates the expression of the glucose transporter‐1 (GLUT1), enabling tumor cells to adapt to low‐glucose conditions and ensuring their survival." (PMID 40365984, 2025). "Similarly, mutations in KRAS, particularly G12C, could alter the tumor’s response to targeted therapies like EGFR-TKIs and MEK inhibitors by activating downstream MAPK and PI3K/AKT/mTOR pathways that promote tumor survival and drug resistance." (PMID 41560751, 2025). "Key markers such as KRAS, BRAF, MSI, and tumor differentiation offer valuable insights into tumor behavior and prognosis." (PMID 40740242, 2025). "Altered NOTCH signaling further promotes crosstalk with the KRAS and EGFR signaling pathways, amplifying tumor proliferation and invasion while remodeling the tumor microenvironment to favor immune evasion and angiogenesis." (PMID 41451346, 2025). "In the non-responder tumors, these proliferation-associated pathways markedly increased alongside activation of KRAS signaling and the UPR, known to enhance tumor survival and chemoresistance under stressful conditions." (PMID 41392193, 2025). "In KRAS-mutant CRC cells, recent research has highlighted distinct metabolic adaptations that support tumor growth." (PMID 40606980, 2025). "Methylation and expression data were correlated to tumor MSI and KRAS status as well as to demographic and clinicopathological data of patients." (PMID 40357388, 2025). "We analyzed tumor regions of 82 formalin‐fixed paraffin‐embedded (FFPE) tissue sections with 6, 23, 31, and 22 samples from the EML4–ALK, EGFR, KRAS, and WT sample groups, respectively." (PMID 40621945, 2025). "The MLH1 expression was significantly lower in tumor tissue of patients with MSI-H compared to MSS tumors (p = .001) as well as in KRAS wild-type tumors (p = .031)." (PMID 40357388, 2025). "A similar pattern was observed in APC; KRAS mut mice treated with DSS, which exhibited widespread tumor formation throughout the colon." (PMID 41285904, 2025). "These patients represented 10 different tumor types, with the majority being NSCLC (58%) and KRAS wild-type pancreatic cancer (22%)." (PMID 40571731, 2025). "Immunohistochemical analysis of tumor tissues from the combination-treatedcohort revealed a marked reduction in p-ERK expression, confirming suppression ofdownstream KRAS signaling." (PMID 41394580, 2025). "In both the malignant cells of the tumour and immune cells within the microenvironment, activation of NRF2 by electrophilic KRAS inhibitors positively contributes to the clinical efficacy of these drugs by promoting anti-cancer immunity." (PMID 40890297, 2025). "In NSCLC, SOD1 supports KRAS-driven tumor growth, and its inhibition—genetically or by the SOD1-targeting agent ATN-224—reduces tumor burden and increases oxidative stress, with minimal toxicity in normal tissues." (PMID 40867898, 2025). "The upstream MAPK pathway activates downstream ERK through KRAS and BRAF, and collaborates with the PI3K/AKT pathway to enhance the proliferation of tumor cells." (PMID 40989695, 2025). "In summary, these data demonstrate that the inhibition in cellular growth in vitro, observed upon treatment with pan-KRAS “OFF” inhibitors, leads to suppression of tumor growth in vivo in preclinical models of KRAS WT–amplified cancers." (PMID 39711431, 2025). "DSS-treated KRAS mut mice remained tumor-free, but APC and APC; KRAS mut mice developed multiple tumors throughout the colon." (PMID 41285904, 2025).
tumor (continued). "We employed targeted next-generation sequencing to analyze seven actionable driver genes - EGFR, KRAS, NRAS, BRAF, ALK, ROS1, and PIK3CA - in formalin-fixed, paraffin-embedded tumor specimens from Vietnamese NSCLC patients." (PMID 40502411, 2025). "Additionally, we performed GSEA enrichment analysis using tumor-related phenotypes associated with IL1RAP, which revealed significant enrichment in hallmark pathways such as inflammatory response, TNFA signaling via NFKB, KRAS signaling down, and IL6 JAK-STAT3 signaling via." (PMID 40444099, 2025). "And an interesting study reported that the use of KRAS pathway inhibitors, such as KRASG12C inhibitors or SHP2 inhibitors, led to an upregulation of MDSCs infiltration, thereby suppressing anti-tumor T cell immunity." (PMID 40611261, 2025). "KRAS-driven tumors secrete vascular endothelial growth factor (VEGF), promoting angiogenesis and enhancing nutrient and oxygen delivery to the tumor." (PMID 40361439, 2025). "The present study uncovered a rare co-occurrence of KRAS (G13D) and BRAF (V600E) alterations in CRC, highlighting tumor heterogeneity and challenging the assumption that these mutations are mutually exclusive within the studied ethnicity." (PMID 40949797, 2025). "Compared to pan-KRAS siRNA methods, EFTX-G12V showed a more effective inhibition of tumor angiogenesis." (PMID 40805153, 2025). "In a PDAC murine model, the KRAS G12D reversible inhibitor, MRTX1133, when combined with CXCR1/2 inhibitor and anti-LAG3 and anti-41BB antibodies yielded complete tumor regression and prolonged survival in 36% of mice at 6 months." (PMID 40227779, 2025). "Vehicle-treated tumor-bearing mice served as the control group, while Brusatol-treated mice showed markedly reduced Nrf2, BCL-2, Ki67, and KRAS expression in metastatic liver nodules." (PMID 41212415, 2025). "In KRAS- or NRAS-mutant cancers, FTIs failed because the tumor simply utilized geranylgeranyltransferase to prenylate RAS instead." (PMID 40335986, 2025). "Aberrations in pathways such as KRAS signaling up, Myc Targets I, and TNF-Alpha signaling can create a tumor-promoting environment and lead to tumorigenesis." (PMID 39801521, 2025). "Consequently, we speculate that in the high PRTFDC1 expression group, tumor cells may be more reliant on the purine nucleotide salvage pathway to promote proliferation, rather than on the signaling pathways activated by KIT, NRAS, or KRAS mutations." (PMID 40241724, 2025). "This combination therapy aims to restore IFN signaling suppressed by oncogenic KRAS while simultaneously promoting proinflammatory conditions in the TME, ultimately leading to enhanced tumor cell death and immune activation." (PMID 40585984, 2025). "In KRAS-mutant pancreatic ductal adenocarcinoma, concurrent inhibition of WEE1 and ERK demonstrated enhanced tumor growth suppression and apoptosis compared to WEE1 inhibition alone." (PMID 40885709, 2025). "SRGs are predominantly expressed in epithelial tumor cells, driving key oncogenic pathways such as epithelial-mesenchymal transition (EMT), KRAS signaling, and IL6-JAK-STAT3 activation, highlighting their contribution to tumor progression and invasiveness." (PMID 40821814, 2025). "Unsurprisingly, vertical pathway inhibition using the concurrent inhibition of KRAS G12C and SHP2 has proven effective in overcoming adaptive feedback resistance across multiple tumor histologies in preclinical studies." (PMID 40940900, 2025).
tumor (continued). "In our study, we observed that patients with the KRAS G12C mutation exhibited significantly poorer survival compared to other patient groups suggesting a more aggressive disease and/or difficulty to treat the tumor with complex mutational landscape, at least without effective targeted therapies." (PMID 38785486, 2024). "The upregulation of LIN28 accelerates the progression of various cancers via reciprocal regulation of the tumor suppressor miRNA, let-7, which suppresses oncogenes such as HMGA2, MYCN, and KRAS." (PMID 39420119, 2024). "Along this line, we previously found mutant KRAS-expressing CRC cells exploited tumor-derived lactic acid to sensitize tumor-specific CTLs to AICD, thereby fostering tumor immune escape and immunotherapy resistance." (PMID 38216551, 2024). "In the F3008 model, when compared to adagrasib treatment alone, treatment with adagrasib plus BI-3406 or cetuximab resulted in a strong downregulation of KRAS and MRAS expression, suggesting durable inhibition of MAPK pathway signaling in residual tumor cells." (PMID 39103541, 2024). "By activating the expression of oncogene KRAS, ASNS promotes the malignant proliferation of tumor cells and leads to tumor progression." (PMID 39445026, 2024). "In mutant KRAS-carrying colon cancer cells, HIPK2 depletion impairs phosphorylation of extracellular signal-regulated kinases 1 and 2 (ERK1/2) and tumor growth in a xenograft model." (PMID 39342278, 2024). "let-7 inhibits tumour development and the RAS-ERK signalling pathway in an autochthonous model of NSCLC driven by activated KRAS (KRASG12D)." (PMID 38637419, 2024). "ST analysis at 7 months after NNK treatment showed that tumour regions had significantly increased expression of Krt8 and Plaur and had spatially overlapping KAC and KRAS signatures." (PMID 38418883, 2024). "(2014) have reported an important function for EGFR ligands like AREG in mediating the communication between KRAS‐mutant and KRAS‐wild type cells in heterogeneous cetuximab‐resistant CRC tumours." (PMID 38887984, 2024). "All ADCs inhibited tumor growth in KRAS mutant EREG-high CRC cell line and patient-derived xenografts and were well tolerated, though the H231-EGC-qDuoDM gluc ADC showed increased tumor growth inhibition and survival." (PMID 40727266, 2024). "Editing the KRAS gene using CRISPR-Cas9 technology can lead to the activation of the P21 protein, a well-known tumor suppressor." (PMID 38195537, 2024). "Moreover, RAS(ON) multi-selective inhibitors could also provide therapeutic benefit in combination with mutant-selective KRAS inhibitors to improve anti-tumour response by blocking adaptive pathway reactivation and preventing escape through emergence of secondary oncogenic RAS or RTK mutations." (PMID 38589574, 2024). "In a landmark study by Yao and colleagues, in transgenic mice models of PDAC, oncogenic KRAS induced SDC1 cell surface overexpression, where it regulated macropinocytosis, a crucial metabolic pathway that fuels PDAC cell growth and promotes tumor progression." (PMID 39263943, 2024). "In summary, all the pathways identified to be downregulated in NRAS, KRAS, and HRAS mutant cancer cell lines upon BAY 11-7082 treatment are prooncogenic and have shown to promote different aspects of tumor growth and progression." (PMID 38982514, 2024). "The expression of oncogenic KRAS or AKT stimulates changes in histone acetylation, which precedes tumor development." (PMID 39588377, 2024).
tumor (continued). "The identification of these accessible regions within the KRAS protein structure may herald significant expansion of the therapeutic target landscape and provide a greater range of pharmacological interventions aimed at inhibiting KRAS-driven cellular proliferation within tumor settings." (PMID 39001451, 2024). "A study shows that siRNA targeting KRAS inhibits the proliferation of CRC cells and slows tumor growth in mouse models." (PMID 39857631, 2024). "However, in the presence of SMARCA4 and KRAS mutations, a shorter survival period was previously observed, which could be attributed to the lower PD‐1 expression and infiltration of CD8+ T cells in the tumor stroma." (PMID 39322625, 2024). "With both apoptosis and cuproptosis induced by Cu-MOF in KRAS mutant NSCLC cells, an effective anti-tumor effect in vivo was observed, demonstrating its feasibility for lung cancer therapy." (PMID 39237931, 2024). "However, the presence of miR-143 in tumor tissue may indicate that not all patients were KRAS-positive (KRAS mutations are observed in 40–45% of CRC patients or that the clinical samples were contaminated with KRAS-negative cells." (PMID 39001526, 2024). "KRAS, NRAS and BRAF testing on tissue was performed with real-time PCR and revealed a wild-type tumor." (PMID 39064004, 2024). "For example, both IL-6 and CXCL8 are reported to be elevated in KRAS-driven STK11-null LUADs and proposed to promote tumor immune evasion." (PMID 37968341, 2024). "Tumor genomic factors may not be the main contributor for KRAS mutation allele specificities." (PMID 38310130, 2024). "This was recently supported by preclinical evidence showing tumour regressions in PDAC models following pharmacologic inhibition of KRAS(G12D)." (PMID 38588697, 2024). "The proliferation, invasion, and tumor properties of intestinal epithelial cells (IECs) derived from human colorectal cancer cells (CRC) and carcinogenic KRAS are inhibited by SHP2 silencing." (PMID 38504984, 2024). "The authors also confirmed that TGF-β signaling contributed to the bypass of the KRAS pathway by promoting the Epithelial-Mesenchymal transition, and the activation of RTK-PI3K-AKT signaling was another potential pathway for promoting tumor cell growth." (PMID 38982491, 2024). "In addition, the deletion of MTAP and CDKN2A/B genes is more frequent in cell lines than in tumor samples and may represent a key driving event in the absence of KRAS/BRAF/NRAS mutations." (PMID 38669365, 2024). "KRAS mutations, such as G12D, G12V, and G12R, confer resistance to guanosine triphosphate (GTP) hydrolysis, leading to the constitutive activation of KRAS and downstream signaling pathway RAF-MEK-ERK and PI3K-AKT-MTOR that support tumor proliferation." (PMID 39329989, 2024). "Mutant KRAS not only plays a critical role in the initiation of PDAC development, but mutant KRAS is also required to maintain tumor growth." (PMID 38800401, 2024). "KRAS contributes to the progression of PDAC through various mechanisms, including malignant transformation, tumor maintenance, metabolic reprogramming, metastasis, stromal proliferation, and dysregulation of immune cells." (PMID 38600093, 2024). "We further conducted RNA sequencing analyses to identify novel genes and pathways altered by BAY 11-7082 treatment in context of NRAS, KRAS, and HRAS mutant cancer cells which leads to tumor growth inhibition." (PMID 38982514, 2024). "We observed a significant tumor-suppressive effect in xenograft tumors treated with a combination of I3C and SHP099 in SW620 (KRAS-mutant), RKO (BRAF-mutant), and Caco-2 (wild type) cells." (PMID 39014007, 2024). "Mutant KRAS drives PDAC development and promotes tumor cell proliferation via altered metabolic pathways or activation of Wnt and MAPK pathways." (PMID 39187784, 2024).
tumor (continued). "For example, cancer RNA biomarkers such as KRAS, PCA3, PIK3CA mutants, EGFRvIII, FOLH1, KLK2, KLK3, EML4-ALK, and NYP have been reported to be sequestered by platelets that actively uptake tumor-derived material." (PMID 39274207, 2024). "KRAS is the major oncogenic driver for PDAC tumorigenesis and is also required for tumor maintenance." (PMID 38800401, 2024). "KRAS inhibition can also lead to increased activation of type I and II IFN responses in cancer cells, which are crucial for anti-tumour immune responses." (PMID 39322643, 2024). "In the KRAS-mutant group, ADAM8 expression appeared to be elevated in the KRAS-mutant tumor group compared to the KRAS wild-type tumor group." (PMID 39329961, 2024). "By the same criteria, the onco-signaling genes AURKA, KRAS, and MYC were up-regulated in over 90%, 60%, and 50% of all tumor types, respectively." (PMID 38649187, 2024). "Recently, combination of KRAS inhibitor AMG510 and anti-PD-1 monotherapy delayed tumor growth, with complete regression in nine of ten tumors and generated most attention." (PMID 38402201, 2024). "Accordingly, higher EREG and AREG expression are associated with low CpG island methylator phenotype (CIMP) status as well as WT KRAS/BRAF, left-primary tumor location (PTL), and microsatellite stability (MSS) versus microsatellite instability (MSI)." (PMID 40727266, 2024). "RNA interference technologies such as siRNA and ASO can target oncogenes such as KRAS and BCL-2 to inhibit tumor growth and progression." (PMID 39857631, 2024). "Several tumor hallmarks, such as mTORC1, PI3K-AKT-mTOR and KRAS, were activated in MPC3, and other tumor biological processes, including hypoxia, peroxisomes, MYC targets and oxidative phosphorylation, were upregulated in MPC3." (PMID 38486026, 2024). "The anti-tumor efficacy of the combined treatment with trametinib and PD-1 blockade was investigated in KRAS-mutant LUAD mouse models, and the effects on the tumor immune infiltrate were analyzed by flow cytometry and immunohistochemistry." (PMID 38643157, 2024). "siRNA and ASO technologies can target genes like KRAS and EGFR, effectively inhibiting tumor cell proliferation and metastasis, and significantly enhancing treatment outcomes." (PMID 39857631, 2024). "Here the authors show that F. nucleatum is enriched preferentially in patients with KRAS p.G12D mutant CRC and that it promotes colorectal tumorigenesis in preclinical models by binding DHX15 on tumor cells." (PMID 38402201, 2024). "Tumor cells with overactivated PI3K, Akt, mTOR, KRas, and c‐Myc positively regulate glutamate metabolism to produce α‐KG, which enters the TCA cycle and provides energy through GLUD or transaminase catalysis." (PMID 39584783, 2024). "Patient 139 showed a profile with extensive MEI in the tumor and harbored a CDK6 ecDNA and KRAS BFB." (PMID 38744814, 2024). "Similarly, in another study, CRC patients with concomitant mutations of KRAS and PIK3CA lead to poor clinicopathological parameters, including the location of the tumor at the proximal colon, the poorly differentiated state of the tumor, and significantly elevated levels of CA-199 and CA125." (PMID 39056802, 2024). "In a study on KRAS-mutant LUAD cells, it was found that SLC7A11 is overexpressed in these cells and mediates tumor progression." (PMID 38705513, 2024).